RALA (RAS like proto-oncogene A)
Description:
Multifunctional GTPase involved in a variety of cellular processes including gene expression, cell migration, cell proliferation, oncogenic transformation and membrane trafficking. Accomplishes its multiple functions by interacting with distinct downstream effectors. Acts as a GTP sensor for GTP-dependent exocytosis of dense core vesicles. The RALA-exocyst complex regulates integrin-dependent membrane raft exocytosis and growth signaling. Key regulator of LPAR1 signaling and competes with GRK2 for binding to LPAR1 thus affecting the signaling properties of the receptor. Required for anchorage-independent proliferation of transformed cells. During mitosis, supports the stabilization and elongation of the intracellular bridge between dividing cells. Cooperates with EXOC2 to recruit other components of the exocyst to the early midbody. During mitosis, also controls mitochondrial fission by recruiting to the mitochondrion RALBP1, which mediates the phosphorylation and activation of DNM1L by the mitotic kinase cyclin B-CDK1.
Synonyms: RAL; HINCONS
Tractability: Small molecule: a structure with a bound ligand is known; it has a binding pocket of medium quality. Antibody: UniProt places it where antibodies can reach, with high confidence; its Gene Ontology location is reachable by antibodies, with high confidence; the Human Protein Atlas places it where antibodies can reach. PROTAC: ubiquitination databases record sites on it; its protein half-life has been measured.
Target class: Enzyme; Hydrolase
Gene: Protein-coding gene on chromosome 7 (39,623,445 to 39,708,124, forward strand). Ensembl gene ENSG00000006451.
Subcellular location: Cell membrane; Cleavage furrow; Midbody, Midbody ring; Mitochondrion
Subcellular location (Human Protein Atlas): Plasma membrane; Focal adhesion sites
Pathways (Reactome):
Immune System: Gene and protein expression by JAK-STAT signaling after Interleukin-12 stimulation
Signal Transduction: p38MAPK events
Vesicle-mediated transport: Translocation of SLC2A4 (GLUT4) to the plasma membrane
Gene Ontology:
Molecular function: ATPase binding; Edg-2 lysophosphatidic acid receptor binding; GDP binding; GTP binding; GTPase activity; myosin binding; protein binding; ubiquitin protein ligase binding; G protein activity
Biological process: membrane raft localization; positive regulation of epidermal growth factor receptor signaling pathway; positive regulation of filopodium assembly; positive regulation of mitochondrial fission; protein localization to mitochondrion; Ras protein signal transduction; receptor internalization; regulation of actin cytoskeleton organization; regulation of exocytosis; chemotaxis; signal transduction; neural tube closure; regulation of postsynaptic neurotransmitter receptor internalization
Cellular component: cell surface; cleavage furrow; endocytic vesicle; extracellular exosome; focal adhesion; mitochondrion; plasma membrane; cytoplasmic vesicle membrane; Flemming body; membrane; Schaffer collateral - CA1 synapse; synaptic membrane
Genetic constraint (gnomAD): Loss-of-function variants: 5 observed, 19.49 expected, observed/expected ratio (o/e) 0.26, 90% interval 0.13 to 0.54. The upper end of that interval is the gene's LOEUF score, 0.54, which puts it in group 2 of 6, group 1 being the genes least tolerant of losing a copy. Missense variants: 91 observed, 239.96 expected, observed/expected ratio (o/e) 0.38, 90% interval 0.32 to 0.45. Synonymous variants: 73 observed, 83.89 expected, observed/expected ratio (o/e) 0.87, 90% interval 0.72 to 1.06.
Gene-disease validity (ClinGen):
ClinGen rates the evidence that RALA causes each of these diseases.
complex neurodevelopmental disorder (autosomal dominant): Definitive. A disorder that involves more than one phenotype associated with the central nervous system, including but not limited to intellectual disability, autism, and seizures (epilepsy).
Homologues: Orthologues: chimpanzee RALA (100% identical), macaque RALA (100% identical), mouse Rala (99% identical), rat Rala (99% identical), dog RALA (99% identical), guinea pig RALA (99% identical), pig RALA (99% identical), tropical clawed frog rala (98% identical), zebrafish ralaa (96% identical), zebrafish ralab (92% identical). Paralogues in human: RALB (82% identical), RRAS2 (47% identical), HRAS (46% identical), KRAS (46% identical), NRAS (45% identical), RAP1B (44% identical), RAP1A (44% identical), RRAS (44% identical), MRAS (43% identical), RIT1 (42% identical), RAP2B (39% identical), RIT2 (39% identical), and 23 more.
Diseases named in the same sentence as RALA in open-access papers:
RALA is named in the same sentence as 95 diseases in open-access papers, as found by Europe PMC text mining. Sharing a sentence is not in itself a finding about the gene and the disease. The quoted sentences say what the papers report.
pancreatic cancer (12 papers, 2011 to 2025). "Using KRAS2 mutants, they reported that the loss of RalA function inhibits the tumorigenicity of pancreatic cancer cells, which is dependent on CDK5." (PMID 37993880, 2023). "RalA and RalB were shown to be activated in pancreatic cancers, aggressive malignancies with high frequency of Ras mutations." (PMID 21714887, 2011). "As for in pancreatic cancers, RALA is essential for tumor growth, and RALA and RALB are both required for tumor invasion." (PMID 37250144, 2023). "Dinaciclib is an inhibitor of CDK5, an activator of the RALs, shown to reduce pancreatic cancer initiation, progression and metastasis in mouse xenograft models by reducing activation of RALA and RALB." (PMID 35626682, 2022). "Additional investigations support the idea that RALB plays a more important role in pancreatic cancer progression than RALA." (PMID 35626682, 2022). "In pancreatic cancer, RALA and B have discrete roles with RALA supporting anchorage independent growth and tumor growth, while RALB is required for invasion and lung colonization." (PMID 34118960, 2021). "Recent evidence shows that inhibition of RalA expression suppresses the transformation and growth of human pancreatic cancer cells." (PMID 33917100, 2021). "Downregulation of Gal-3 in MPanc96 pancreatic cancer cells was associated with decreased phosphorylation of AKT, ERK1/2 and also RalA-GTP activity." (PMID 22900040, 2012). "Indeed, inducible knockdown of RALA in a primary pancreatic tumor model induced regression." (PMID 41072768, 2025). "Among all synthesized compounds, 123a exhibited powerful RalA inhibition and led to the accretion of RSO and passive spread of pancreatic cancer cells via tempted mitochondrial damage and apoptosis in pancreatic tumor cells." (PMID 37570735, 2023). "Thus, CDK5 inhibitors may act as RalA and RalB inhibitors in pancreatic cancer." (PMID 29047224, 2017). "Later, it was found that RALA, but not RALB, supports anchorage-independent growth in the pancreatic cancer cell line MiaPaCa2." (PMID 35626682, 2022). "Although the exact molecular mechanism was not delineated, CDK5 may regulate the activation of RalA and RalB by controlling the function of either RalGEFs or RalGAP, suggesting CDK5 as a possible target for pancreatic cancer." (PMID 37993880, 2023).
breast cancer (11 papers, 2015 to 2024). A primary or metastatic malignant neoplasm involving the breast. "To evaluate the general prognostic importance of RALA and RALB in BC subtypes associated with RAS activation, we generated Kaplan–Meier survival plots using data from the KM Plotter breast cancer metacohort." (PMID 39272901, 2024). "Recently, it has been proven that FOXD1 is significantly elevated in breast cancer cells and tissues, and it promotes migration and metastasis of BC cells by upregulating RalA via directly bound to RalA promotor." (PMID 37906341, 2023). "For example, RALA is required for invasion of MDA-MB-231 breast cancer cells, but in bladder cancer RALB is found to support invasion." (PMID 35626682, 2022). "Our study demonstrates that Ral GTPases enhance the formation of lung metastasis in mouse models, by promoting the secretion of exosomes within primary tumors, while RalA/B expression levels correlates with metastasis in human breast cancer." (PMID 33404012, 2021). "Using a large cohort of breast cancer patients with metastatic progression from the Cancer Genome Atlas (TCGA), we found that high expression of either RalA or RalB is significantly correlated with reduced survival." (PMID 33404012, 2021). "Automated quantification of RalA/B expression levels by immunohistochemistry in primary tumors of breast cancer patients unraveled overexpression of both proteins in tumors from patients with metastasis." (PMID 33404012, 2021). "We have previously shown that RalA and RalB control EV secretion in aggressive 4T1 mammary tumor cells that reliably mimics the aggressive phenotype of human triple-negative breast cancer." (PMID 33404012, 2021). "Here, we exploited 4T1 cells, an aggressive mammary tumor model that mimics human triple-negative breast cancer to further decipher how RalA/B tune EV secretion mechanisms and thereby control metastatic progression of the disease." (PMID 33404012, 2021). "We measured the number and the surface covered by metastatic foci in serial lung sections and observed that RalA or RalB depletion in mammary tumors drastically reduced their metastatic potency." (PMID 33404012, 2021). "Our data suggest that RILP suppresses the invasion of breast cancer cells by interacting with RalGDS to inhibit its GEF activity for RalA." (PMID 26469971, 2015). "Our results suggest that RILP suppresses the invasion of breast cancer cells by modulating the activity of RalA through interaction with RalGDS." (PMID 26469971, 2015). "The earliest studies exploring RAL-GTPases in breast cancer suggested that RALA may be involved in tamoxifen resistance in breast cancer cells and EGFR-independent growth." (PMID 35626682, 2022). "Finally, we identify the adhesion protein CD146/MCAM as a key EV cargo controlled by RalA and RalB and demonstrate that it conveys, in part, the pro-metastatic function to EVs by controlling the lung tropism of breast cancer EVs." (PMID 33404012, 2021). "Having identified RalA and RalB as important regulators of EV secretion in breast cancer cells, we next investigated whether such a function could impact metastasis." (PMID 33404012, 2021). "Finally, we show that high levels of RalA and RalB correlated with poor prognosis suggesting a unified mechanism for human breast cancer metastasis." (PMID 33404012, 2021). "Likewise, in 4T1 mouse mammary tumor cells, knockdown of the mammalian homologs Ras like proto-oncogene A (RalA) and RalB reduced the secretion of exosome-like vesicles." (PMID 28733901, 2018). "Taken together, RILP may inhibit the invasion of breast cancer cells by modulating the activity of RalA through the interaction with RalGDS to negatively regulate the GEF function." (PMID 26469971, 2015). "Importantly, we further showed that RalA/B modulate the levels of secreted EVs in models that are relevant to human breast cancer suggesting that these GTPases could influence disease progression through EVs release." (PMID 33404012, 2021).
breast cancer (continued). "Here, we found that RALA mRNA expression correlates with poorer clinical outcomes across BC and specifically within the HER2+ and TNBC/basal BC subsets in the KM Plotter breast cancer metacohort." (PMID 39272901, 2024). "Recent work by Vincent Hyenne’s group has found a critical role for RALA and RALB in extracellular vesicle trafficking, driving breast cancer metastasis." (PMID 35626682, 2022). "It has previously been reported that RALA and RALB regulate pro-metastatic extracellular vesicle secretion in the 4T1 mouse mammary tumor model, and contradictory effects of RALB silencing, with RALB loss decreasing tumor volume in vivo but increasing proliferation in vitro, were also observed." (PMID 39272901, 2024). "We further demonstrate that RalA and RalB promote lung metastasis without affecting the invasive potential of breast carcinoma." (PMID 33404012, 2021). "Therefore, RalA/B seem to promote metastasis independently of cell invasion and are likely to promote metastasis of aggressive breast cancer cells non-cell autonomously by inducing pro-metastatic micro-environmental changes." (PMID 33404012, 2021). "Finally, RalA, RalB, and MCAM/CD146, are factors of poor prognosis in breast cancer patients." (PMID 33404012, 2021).
bladder cancer (9 papers, 2011 to 2022). "Smith and colleagues, in 2007, demonstrated, in bladder cancer, that the overexpression of RalA is associated with tumors of high-stage and grade." (PMID 34944949, 2021). "RalA overexpression is associated with several different types of human cancers, in particular bladder cancer, which represents a major epidemiological problem and whose incidence continues to increase each year." (PMID 34944949, 2021). "Analysis of human bladder cancer cell lines also revealed RalA activation, which cannot be caused by protein mutations affecting its intrinsic GTP-binding activity." (PMID 34944949, 2021). "It is known in bladder cancer cells that the loss of E-cadherin interaction with RalGDS (an activator of RalA) results in robust endocytosis during blebbishield formation." (PMID 28851898, 2017). "Substantial literature on RAL-GTPases in bladder cancer has been published, supporting divergent roles for RALA and RALB." (PMID 35626682, 2022). "In MEFs and bladder cancer cells, the downregulation of both RalA and RalB activities is required to significantly reduce growth." (PMID 35897776, 2022). "It has been previously demonstrated that RalGPS GEFs have a prominent role in RalA activation in 5637 bladder cancer cell lines." (PMID 34944949, 2021). "In bladder cancers RalB is reported to be more active than RalA in some studies, with a reported role in migration, proliferation and anchorage independence as well." (PMID 27269287, 2016). "It was previously shown that RalA depletion downregulated cell surface highly-glycosylated protein CD24 expression in bladder cancer cell lines." (PMID 21714887, 2011). "RALA also inhibits cancer cell migration in certain types of tumors, such as bladder cancer." (PMID 36466919, 2022). "Interestingly, RALA expression was up-regulated in tumor tissues of bladder cancer by analysis of the TCGA database." (PMID 36466919, 2022). "CD24 has been shown to be RalA-regulated in a model of bladder cancer-derived cell lines." (PMID 21714887, 2011). "Genes up-regulated after knockdown of RALA or RALB [GeneiD=5898;5899], which were also differentially expressed in bladder cancer compared to normal bladder urothelium tissue." (PMID 28423528, 2017). "Furthermore, in 2018, our group demonstrated, in 5637 bladder cancer cell lines, the role of RalGPS2 (Ral GEF with PH domain and SH3-binding motif 2), a Ras-independent guanine exchange factor (GEF) for the GTPase RalA, in TNTs formation under low serum condition." (PMID 34944949, 2021). "TNTs observed in 5637 cells are functionally active and involved in mitochondrial trafficking; here, we demonstrated that TNTs in bladder cancer cells are also able to transport molecules important for TNTs development, such as LST1 and RalA, but not RalGPS2." (PMID 34944949, 2021).
melanoma (9 papers, 2016 to 2024). A malignant, usually aggressive tumor composed of atypical, neoplastic melanocytes. "The main types of cancer with mutations in RALA gene are Colorectal Adenocarcinoma, Melanoma and Burkitt lymphoma." (PMID 36466919, 2022). "In certain cancers, such as pancreatic cancer, melanoma, and lung cancer, both RALA and RALB have been found to promote tumorigenicity." (PMID 39272901, 2024). "Early investigations of the RAL GTPases in melanoma have suggested that RALA is the predominant paralog." (PMID 35626682, 2022). "RalA activation has a critical effect on Ras-mediated human cell carcinogenesis 17, and this protein has been suggested to participate in the development of diverse cancers 38 such as melanoma 39, colorectal cancer 40, and lung cancer." (PMID 36923939, 2023). "Among them, the RALA c.G482A somatic variant we identified has been reported to be associated with adult T-cell lymphoma leukemia and malignant melanoma, and no studies have been performed to associate them with neurological diseases." (PMID 35846790, 2022). "In almost all cancer types examined (pancreas, colon, lung, bladder, prostate, melanoma), increased overexpression and/or activation of both RalA and RalB have been observed in patient tumor samples compared with normal tissues, regardless of their Ras mutation status." (PMID 30320548, 2018). "The two highly homologous small GTPases, RAS like Proto-oncogene A (RALA) and B (RALB), activated downstream of RAS, have been implicated in tumor growth and metastasis in a wide variety of cancer types including colorectal cancer, lung cancer, melanoma, and BC." (PMID 39272901, 2024). "Assessment of the levels of active GTP-bound RALA and GTP-bound RALB demonstrated that independently derived melanoma cell lines have much higher GTP-RALA levels and essentially absent GTP-RALB." (PMID 35626682, 2022). "However RALA and RALB are overexpressed in a number of tumors, most notably NSCLC and melanoma." (PMID 27713118, 2016).
prostate carcinoma (9 papers, 2012 to 2024). A carcinoma that arises from epithelial cells of the prostate gland. "This mechanistic study revealed that redistribution of AQP3 in prostate cancer occurs through RalA/PKA/cAMP signaling pathways." (PMID 36672280, 2023). "It has also been demonstrated that Myc-associated zinc finger protein (MAZ) promotes prostate cancer metastasis to the bone through transcriptional upregulation of K-RAS and subsequent activation of RALGEF and RALA." (PMID 35626682, 2022). "RALA was demonstrated to regulate VEGF-C expression in prostate cancer cells undergoing androgen ablation." (PMID 35626682, 2022). "Hazekett and Yeaman demonstrated that the interactions between RALA and the exocyst complex are required for migration and invasion of PC-3 prostate cancer cells." (PMID 35626682, 2022). "In this study, we characterized the serum autoantibody response to the RalA, Ras-like GTPase, in patients with prostate cancer (PCa)." (PMID 27286458, 2016). "We chose PC-3 cells, an invasive human prostate cancer cell line, to investigate the function of RalA-Exocyst interactions in tumor cell migration." (PMID 22761837, 2012). "Most evidence supports RALA as the more important RAL GTPase in ovarian cancer and prostate cancer, while RALB appears to be more important for cancer progression and metastasis in bladder and lung cancers." (PMID 35626682, 2022). "RALA complex enhanced the tumour growth, delaying activity of alendronate in the PC3 xenotransplantation model of prostate cancer." (PMID 35593206, 2022). "In prostate cancer cells, PC-3, AQP3 is translocated from the cytoplasm to the cell membrane after silencing of RAS like proto-oncogene A (RalA)." (PMID 33947079, 2021). "Several other investigations in prostate cancer have focused largely on RALA without complementary investigation of RALB." (PMID 35626682, 2022). "The absence of RalA suppressed cell motility and invasion in prostate cancer cells." (PMID 36672280, 2023).